PHB1 (prohibitin 1)
Diseases named in the same sentence as PHB1 in open-access papers (continued):
Sharing a sentence is not in itself a finding about the gene and the disease.
cancer (67 papers, 2009 to 2025). A tumor composed of atypical neoplastic, often pleomorphic cells that invade other tissues. "In cancer cells, depletion of PHB1 causes defects in proliferation, but little is currently known about the regulation of PHB1 in pulmonary vascular remodeling and PAH." (PMID 34925032, 2021). "PHB1 on the plasma membrane is associated with drug-resistant cancer cells, while PHB1 in the nucleus is associated with tumor suppression." (PMID 34868199, 2021). "Along this line, overexpression of PHB1 results in a higher resistance to apoptosis in different types of cancer cells, while downregulation of PHBs renders cancer cells more susceptible to pro-apoptotic insults, suggesting a pro-tumorigenic role of PHBs." (PMID 26497683, 2015). "Since anchorage-independent growth is a hallmark of cancer cells, we also assessed this phenotype in our cell lines constitutively expressing shRNAs targeting PHB1." (PMID 20856874, 2010). "However, other studies found that PHB1 deficiency accelerated cancer cell growth and decreased cell apoptosis." (PMID 26091791, 2015). "PHB1 is a pleiotropic protein that functions as a growth regulatory molecule in several tissues and is primarily expressed in adipocytes, immune, cancer, and diabetic cells." (PMID 40168274, 2025). "PHB1 has been suggested to play a dual role of pro-cancer/anti-cancer, depending on its dynamic distribution characteristics in different tumor types." (PMID 37210546, 2023). "Given the established role of mitophagy in aging, neurodegeneration, cancer, and inflammation, the functions of PHB1 and PHB2 in mitophagy likely play a mechanistic role in these diseases." (PMID 36593241, 2023). "In human cancer cell lines, Mel56 targets the inner mitochondrial integral membrane prohibitin proteins, PHB1 and PHB2." (PMID 36678474, 2023). "Further, IHC examination on 105 clinical PCa specimens and 5 cancer-adjacent normal tissues showed that PHB1 expression was significantly higher in PCa tissues than that in adjacent normal tissues and was positively correlated with the Gleason score." (PMID 37210546, 2023). "It has been widely reported that PHB1 plays a pro-cancer role in a variety of tumors, but there are few reports on the function of PHB1 in CRPC." (PMID 37210546, 2023). "It has been shown that RocA and Fluorizoline inhibit the activation of the Raf-1/ERK signaling cascade and suppress cancer cell growth and metastasis by binding PHB1." (PMID 36348375, 2022). "PHBs are widely distributed in cells, and PHB1 exerts controversial impacts on cell proliferation in different cancers." (PMID 36348375, 2022). "The role of Phb1 has been shown to be both pro-survival or pro-apoptotic and appears to be cancer type-specific." (PMID 35668443, 2022). "Another study expanded on this finding by revealing that phosphorylated PHB1 at T258 is important for activating CRaf, for the direct interaction between CRaf and PHB1, and for cancer cell invasiveness." (PMID 34868199, 2021). "Together, these findings suggest that PHB1 phosphorylated at T258 by Akt can increase the invasiveness of cancer by direct interaction with Raf-1." (PMID 34868199, 2021). "PHB1 interacts with CRaf (Raf-1), which can activate pathways involving Ras that support cancer and its invasiveness, such as the CRaf/ERK, PI3K/Akt, and RalGEF/Ral pathways." (PMID 34868199, 2021). "Prohibitins (prohibitin 1 and prohibitin 2) have been shown to play critical roles in aging, cancer, obesity, and mitophagy." (PMID 32165613, 2020). "The expression of PHB1 shows an increase in cancer cells, making it a suitable target in cancer therapy." (PMID 32784981, 2020). "Recently, increasing evidence has shown that PHB1 is a tumour suppressor protein and a potential target for cancer therapy." (PMID 30886235, 2019). "While evidence of a role for PHB1 overexpression has been reported in cancer progression, higher levels of PHB2 was found in proliferating cells, including neoplastic tissues." (PMID 31684984, 2019).
cancer (continued). "Recent studies have focused on the phosphorylation of PHB1 at Tyr114, Ser121, Thr258, and Tyr 259124, with Thr258 and Tyr 259 phosphorylation well characterized in cancer cells." (PMID 29784973, 2018). "The level of nuclear PHB1 can be down-regulated upon androgen treatment in cancer cells, indicating that PHB1 has a regulatory role in cell cycle progression." (PMID 29784973, 2018). "In line with the present results, we have previously reported overexpression of KRT8/18 and PHB1 as biomarkers of mouse liver preneoplastic lesions and tumors, showing the highest expression in carcinomas." (PMID 28785378, 2017). "In abrin (ABR)-induced apoptosis of human Jurkat T leukemia cancer cells, downregulation of PHB1 delays ABR-triggered cell apoptosis." (PMID 26091791, 2015). "Using the constitutive expression system pLL3.7, we demonstrated that, in all tested cancer cell lines, numbers of cells, expressing a PHB1 mRNA targeting shRNA were decreased from within a pool of transduced and non transduced cells." (PMID 20856874, 2010). "They found that prohibitin-1 (PHB1) was the driver of decreasing mitochondrial function to produce lower levels of reactive oxygen species, and knocking down PHB1 increased mitochondrial membrane potential and reduced radio resistance in their cancer model." (PMID 40943388, 2025). "Despite the upregulation of PHB1 in a variety of tumors, its signal-dependent dynamic partitioning between subcellular compartments contributes to its dynamic transition between anti-cancer role and pro-cancer role." (PMID 37210546, 2023). "FL3 is a synthetic flavagline drug that inhibits cancer cell proliferation by targeting PHB1." (PMID 37210546, 2023). "Synthetic PHB1 mRNA can prevent DNA synthesis in HeLa cells and healthy fibroblasts, providing evidence that PHB1 transcripts could be a potential treatment for cancer by preventing the replication of DNA in cancer cells." (PMID 34868199, 2021). "However, most of the current knowledge concerning PHB proteins in cancers has been gleaned from studies with prohibitin 1 (PHB1), while studies on the effects of PHB2 have been limited to date, especially in NSCLC 34, 37-40." (PMID 33537079, 2021). "PHB1’s role in metabolism may have importance in cancer because its role as an inhibitor of pyruvate carboxylate facilitates the shifting from oxidative phosphorylation to anaerobic glycolysis." (PMID 34868199, 2021). "Numerous studies showed that PHB1 is a potential target for cancer therapy." (PMID 30886235, 2019). "The role of PHB1 in cancer cell apoptosis has been explored in various studies." (PMID 29784973, 2018). "Moreover, the investigation on paclitaxel resistance in cancer cells demonstrated that ERα promotes PHB1 mitochondrial-to-nuclear translocation to regulate estrogen-dependent paclitaxel resistance." (PMID 29784973, 2018). "It is anticipated that molecules targeting PHB1 and its phosphorylation on the plasma membrane may be effective in decreasing cancer cell metastasis and invasiveness." (PMID 29263933, 2017). "Moreover, they found that PHB1 over-expression induce cellular resistance to chemotherapy by decreasing the sensitivity of cancer cells to apoptosis." (PMID 28427435, 2017). "Perturbation of tyrosine phosphorylation of PHB1 leads to impaired insulin signaling and altered cell metabolism, and these events may eventually lead to the development of type-2 diabetes and cancer." (PMID 29263933, 2017). "However, PHB1 exhibits opposing functions in other cancer types." (PMID 29784973, 2018).
cancer (continued). "In addition, sequencing of the PHB1 3′UTR of different cancer cell lines, including MCF-7, revealed a higher frequency of overall sequence variation in comparison to primary non-cancer cells rather than a predominant expression of a specific T-allele (CS and TR, unpublished)." (PMID 20856874, 2010). "Rocaglamide A, derived from medicinal plants, have been demonstrated to interact directly with PHB1 and thus inhibit the interaction of PHB1 with Raf-1, impeding Raf-1/ERK signaling cascades and significantly suppressing cancer cell metastasis." (PMID 41357231, 2025). "It was reported that PHB1 and PHB2 expression levels are high in most cancer types, for both mRNA and protein." (PMID 37190120, 2023). "In tumor cells, both plasma membrane and mitochondria-located PHB1 play a cancer-promoting role via overactivation of C-Raf/MAPK pathway and anti-apoptosis, while the nuclear PHB1 mainly functions as a tumor suppressor." (PMID 37210546, 2023). "High expressions of PHB1 and PHB2 were reported in 1078 cell lines in the Cancer Cell Line Encyclopedia (CCLE) and were recognized as common essential genes in 1077 of the 1078 tested cell lines (Depmap.org/Portal)." (PMID 37190120, 2023). "The direct importance of CD36 interaction with PHB1/and ANX2 in cancer cells remains to be established." (PMID 35991116, 2022). "Our previous study showed that LPLUNC1 upregulates Prohibitin 1 (PHB1), a pleiotropic protein that functions as a tumour suppressor gene in various cancers." (PMID 30886235, 2019). "A lot of evidence demonstrated that PHB1 and PHB2 are involved in biological processes of cancer development, such as proliferation, apoptosis, and metastasis." (PMID 29784973, 2018). "As PHB1 and PHB2 have been shown to be differentially expressed in multiple cancers, PHB1 and PHB2 are potentially useful as new biomarkers and targets in cancer diagnosis and treatment." (PMID 29784973, 2018). "Most studies have confirmed differential expression of PHB1 and PHB2 in cancers compared to corresponding normal tissues." (PMID 29784973, 2018). "The present study was initiated to determine the role of PHB1 and PHB2 in T- and B-cell malignancies." (PMID 29029444, 2017). "In a 2018 review paper, expression of PHB1 and PHB2 was surveyed in 17 cancer types." (PMID 37190120, 2023). "We speculate that the interaction between PHB-1 and RUVBL-1 will not only have implications in the arena of parasite biology but also shall shed some light on cancer progression." (PMID 36651733, 2023). "A possible role of the PHB1/ANX2/CD36/CAV1 interactome in cancer progression remains to be determined and put into the context of what is known about other proteins, such as FATP1, which also regulate FA transport in cancer cells." (PMID 35991116, 2022). "FoxM1 regulates prohibitin 1 (PHB1) at the transcription and translation levels, which promotes activation of RAF‐MEK‐ERK signaling, leading to the phosphorylation of ERK1/2 to support the continuous proliferation of cancer cells." (PMID 34766149, 2021). "PHB1 and PHB2 levels were higher in these cancer patients than in controls." (PMID 34868199, 2021). "On the other hand, FoxM1 positively promotes ATP binding cassette subfamily a member 2 (ABCA2) expression but is also regulated by the FoxM1/PHB1/RAF‐MEK‐ERK feedback loop, which may induce additional resistance of cancer cells to Taxol." (PMID 34766149, 2021). "Overexpression of PHB1 and PHB2 has been observed in blood-related cancers." (PMID 34868199, 2021).
cancer (continued). "Several publications have showed differential expression of PHB1 and PHB2 in cancer cell lines compared to normal tissues, verifying that PHB1 and PHB2 are involved in biological processes of tumorigenesis, such as cancer cell proliferation." (PMID 33374179, 2020). "As TRIM21 is a RING-finger domain-containing ubiquitin E3 ligase that plays an important role in cancer progression, we hypothesised that TRIM21 might be involved in the blockage of the ubiquitinated degradation of PHB1 by LPLUNC1." (PMID 30886235, 2019). "Translocation of PHB1 and the mitochondrial protein AIF between mitochondria and the nucleus, or from cytoplasm to nucleus, was proposed to be part of the apoptotic signaling in normal and cancer cells, notably following flavagline exposure." (PMID 31684984, 2019). "Furthermore, studies verified that PHB1 and PHB2 are involved in the biological processes of tumorigenesis, including cancer cell proliferation, apoptosis, and metastasis." (PMID 29784973, 2018). "Two small molecule inhibitors, Rocaglamide (RocA) and fluorizoline, derived from medicinal plants, were demonstrated to interact directly with PHB1 and thus inhibit the interaction of PHB with Raf-1, impeding Raf-1/ERK signaling cascades and significantly suppressing cancer cell metastasis." (PMID 29784973, 2018). "Moreover, phosphorylation of PHB1 at Thr258 and Tyr259 induced by AKT is important for cancer metastasis." (PMID 29784973, 2018). "Meanwhile, PHB1 located in the lipid raft of the cell membrane interacts with and activates Raf-1, an evolutionarily conserved oncogene that activates ERK and promotes cancer development." (PMID 29784973, 2018). "PHB1 is regulated by multiple post-translational modifications and its phosphorylation induces PI3K⁄Akt and RAF⁄ERK pathways, as well as TGF-b cell signaling in cancer cells." (PMID 29126391, 2017). "Interestingly, unlike its controversial role in cancer cell proliferation, PHB1 expression levels are significantly correlated with tumor metastasis and poor prognosis according to the current literature." (PMID 29784973, 2018). "The membrane localization of PHB1 has an unusual ability to control apoptosis; it clearly not only functions as a transmembrane signal receptor in the survival of cancer cells and the apoptosis of HSCs but also mediates endocytosis in the induction of apoptosis in the adipose vasculature." (PMID 26091791, 2015). "Moreover, ERAP, a short synthetic peptide, and xanthohumol, a natural product from medical plants, were demonstrated to suppress cancer cell proliferation by targeting PHB224, 25, indicating that drugs targeting PHB1 and PHB2 may be a promising strategy for cancer treatment." (PMID 29784973, 2018).
tumor (59 papers, 2009 to 2025). "Overall, our data underscore that neddylation inhibition as a result of MLN4924 treatment to Phb1-KO mice is associated with tumor regression associated with metabolic reprogramming." (PMID 25650664, 2015). "Prohibitin1 (PHB1) is a target protein that is associated with tumor suppression." (PMID 34452113, 2021). "Despite these indications of a tumor suppressor activity, recent studies have also demonstrated reduced cell proliferation upon loss of PHB1 expression in mouse embryonic fibroblasts and other primary cells; and the rescue of cell proliferation upon overexpression of mitochondrial-targeted PHB2." (PMID 20856874, 2010). "The authors suggested contact between cells were disrupted in tumor cells due to the loss of PHB1." (PMID 20856874, 2010). "Our results are in concordance with another study, wherein a cyclopeptide derived from D. auricularia exhibited a cytotoxic effect on tumor cells, leading to apoptosis; the authors suggest that this occurs through prohibitin-1." (PMID 39852534, 2025). "PHB1 protein levels were significantly upregulated in tumor tissues compared to matched normal counterparts (p < 0.05; n = 4 pairs)." (PMID 40723377, 2025). "Immunofluorescence staining further confirmed the co-enrichment of DIRAS1 and PHB1 in CRC tumor tissues relative to adjacent and distant normal tissues." (PMID 40723377, 2025). "In summary, our results firstly demonstrated that ADT triggered the anti-/pro-tumor role switch of PHB1 in CRPC by upregulating PHB1 and more importantly, inducing its nucleus-cytoplasmic translocation." (PMID 37210546, 2023). "Consistent with the expected role of Phb1 as a tumor suppressor gene and regulator of cell proliferation, cell viability increased when Phb1 expression was 50% of the normal level." (PMID 36310362, 2022). "In contrast, dephosphorylating PHB1 at T258 reduced tumor cell invasiveness and metastasis and decreased epithelial-mesenchymal transition." (PMID 34868199, 2021). "PHB1 has been well identified as a potential tumor suppressor with antiproliferative activity in mammalian cells." (PMID 33374179, 2020). "Some types of tumor overexpress PHB1 in the nucleus and some in mitochondria, whereas some of them do not express it at all." (PMID 33354575, 2020). "Depletion of PHB1 rescued the anti-tumour effects of LPLUNC1, which suggested that LPLUNC1 inhibited NPC cell proliferation partly through a PHB1-mediated mechanism." (PMID 30886235, 2019). "In the current study, we found that PHB1 over-expression significantly inhibited the proliferation of NPC cells in vitro and in vivo, suggesting that PHB1 is a tumour suppressor gene in NPC." (PMID 30886235, 2019). "The average weight of PHB1 over-expression tumours was significantly lower than that of the control group (P < 0.001)." (PMID 30886235, 2019). "Together our data suggest that LPLUNC1 exerts a tumour-suppressive role by downregulating the NF-κB pathway via inhibition of PHB1 ubiquitination and degradation mediated by TRIM21." (PMID 30886235, 2019). "Our findings further revealed a novel mechanism underlying the anticancer effect of LPLUNC1 and clarified that PHB1 was a tumour suppressor in NPC and provide potential targets for NPC diagnosis and treatment." (PMID 30886235, 2019). "PHB1 was originally cloned from regenerating livers and was thought to be a tumour suppressor (hence its name)." (PMID 30886235, 2019). "Depletion of PHB1 significantly attenuated the anti-tumour effects of LPLUNC1 in NPC cells, and the inhibitory effect of LPLUNC1 on NF-κB activity was thus reversed." (PMID 30886235, 2019).